CHFR (checkpoint with forkhead and ring finger domains)
Diseases named in the same sentence as CHFR in open-access papers (continued):
Sharing a sentence is not in itself a finding about the gene and the disease.
tumor (30 papers, 2008 to 2025). "The mitotic checkpoint gene (CHFR) (Checkpoint with Forkhead-associated and Ring finger domains is a G2 phase/mitosis checkpoint and tumor-suppressor gene." (PMID 29515792, 2018). "Checkpoint with Forkhead-associated and Ring finger domains (CHFR) is a G2/M checkpoint and tumor-suppressor gene." (PMID 29312643, 2017). "Based on these results, tumor CHFR promoter hypermethylation is not only a diagnostic biomarker for CRC, but also a prognostic marker." (PMID 29179506, 2017). "The higher level of CHFR methylation is significantly associated with worse overall survival compared to patients with a lower level of CHFR tumor DNA methylation." (PMID 29179506, 2017). "Checkpoint with fork-head associated and ring finger (CHFR) is a mitotic checkpoint gene with tumor-suppressor functions." (PMID 24348823, 2014). "The loss of CHFR mRNA expression is a consequence of promoter methylation, suggesting a tumor suppressor role for this gene in gastrointestinal carcinogenesis." (PMID 18335050, 2008). "To date, two possible molecular pathways have been considered as the mechanisms underlying the tumor suppressor function of CHFR." (PMID 18335050, 2008). "Comprehensive bioinformatics analysis was performed to verify that the checkpoint with forkhead associated and ring finger domains (CHFR) gene is a reliable candidate oncogene, which is overexpressed in ccRCC metastatic tumor tissue, and that high expression levels of CHFR indicate a poor prognosis." (PMID 34539751, 2021). "The tumor suppressor role of CHFR was suggested to be a consequence of its ability to cause degradation of HLTF and protect against HLTF-mediated cell migration by modulating HLTF’s regulation of expression of plasminogen activator inhibitor-1 (PAI-1) implicated in tumor invasion and metastasis." (PMID 25906194, 2015). "Methylation of the retinoic acid receptor β gene, RARB, and that of the checkpoint with forkhead and ring finger gene, CHFR, was associated with tumour stage (RARB: 51·9 per cent for T1–2 versus 33·9 per cent for T3–4, P < 0·001; CHFR: 5·5 per cent for T1–2 versus 12·6 per cent for T3–4, P = 0·005)." (PMID 25052224, 2014). "Thus, loss of CHFR causes errors in chromosome segregation that can lead to neoplasia." (PMID 29312643, 2017). "Our data from animal experiments demonstrated that CHFR inhibited tumor growth and ki67 expression, and promoted NRF2 expression, the activation of AKT and ERK, and lung metastasis of GC cells nude mice." (PMID 37024798, 2023). "Our results suggested that CHFR was not only acted as a tumor suppressor by inhibiting cell cycle progression, but also promoted the cell migration and invasion by activating AKT and ERK in a NRF2-ROS axis." (PMID 37024798, 2023). "Multiple studies have indicated that CHFR functioned as a tumor suppressor by regulating numerous important proteins as it was also a RING-type E3 ubiquitin (Ub)-ligase." (PMID 37024798, 2023). "Another E3 ubiquitin ligase, CHFR, inhibits immune-resistance, drug-resistance, and stem-like phenotype in tumor cells through promoting ubiquitin-mediated degradation of HDAC144." (PMID 37441600, 2023). "Dma1 belongs to a small class of proteins carrying both FHA and RF domains and has two homologs in humans, a tumor suppressor CHFR and RNF840,41." (PMID 36138017, 2022). "Consistent with its expression, CHFR plays an important role in tumor suppression through blocking cell cycle progression or inhibiting metastasis." (PMID 34462429, 2021). "The TCGA dataset revealed that CHFR was highly expressed in the tissues of patients with higher tumor histological grades, advanced primary tumor pathological stages, lymph node metastasis, distant metastasis, and advanced pathological stages." (PMID 34539751, 2021). "In ccRCC tumor tissues, although the overall methylation level of CHFR increased, the gene expression level was also significantly increased." (PMID 34539751, 2021).
tumor (continued). "Based on TCGA datasets, CHFR gene expression levels were significantly upregulated in tumor tissue compared with those in adjacent control normal tissue." (PMID 34539751, 2021). "There is compelling evidence that reduced CHFR expression is a promising biomarker that can improve the management of multiple tumor types." (PMID 24375389, 2014). "In the present study, mRNA expression of CHFR was assessed in 40 primary tumor samples using RT-PCR, which showed a variety of CHFR expression levels." (PMID 24348823, 2014). "In fact, CHFR knockout mice are cancer-prone, indicating that the CHFR gene functions as a tumor suppressor." (PMID 24348823, 2014). "Larger tumours (median diameter 40 mm or more) had higher methylation levels of checkpoint with forkhead and ring finger gene, CHFR, as did more advanced lesions (pT3–4)." (PMID 25052224, 2014). "Here we summarize the current knowledge of altered CHFR expression in cancer, the impact on tumor biology and implications for personalized cancer treatment." (PMID 24375389, 2014). "Originally, CHFR was shown to function as a mitotic checkpoint protein required for tumor suppression, partly through ubiquitination and targeting of AURA for degradation in the proteasome." (PMID 23351307, 2012). "If the E3 ligase activity of CHFR is more important for growth suppression, as we initially expected, the core region of this tumor suppressor that is required for its anti-proliferative effects was anticipated to be the RF domain." (PMID 18335050, 2008). "This discrepancy may have resulted from the fact that promoter methylation of CHFR can inhibit its tumor suppressive function as well as it can promote sensitivity of irinotecan." (PMID 40666491, 2025). "CHFR was considered as a tumor suppressor in many cancer types." (PMID 37024798, 2023). "In addition, analysis of 98 basal-like 1 subtype tumor samples also showed that high CHFR expression levels positively correlates with distant relapse-free survival of those patients (P = 2 × 10−4)." (PMID 34462429, 2021). "Several studies have supported the role of CHFR as a potential tumor suppressor." (PMID 24012691, 2013). "In our studies as we found TOPK, an oncogene and PTEN, a well known tumor suppressor to play an intricate role in CHFR functions we speculate that these two proteins may partially contribute to CHFR tumor suppressor function as well." (PMID 24012691, 2013). "In addition, the role of CHFR as a tumor suppressor has been substantiated by CHFR knock-out mice, which are cancer prone and develop spontaneous tumors." (PMID 24012691, 2013). "There is increasing evidence that CHFR plays a crucial role as a checkpoint in the cell cycle, regulating the entry into mitosis to prevent the proliferation of cells that have damage in their genome, and it has been proposed as a potential biomarker for several tumor types." (PMID 34869418, 2021). "CHFR was considered a key element for NANOG mediated multi-resistance and stem-like phenotype in immune-edited tumor cells." (PMID 35813831, 2022). "CHFR is a RING-type E3 ubiquitin ligase that acts as a mitotic-checkpoint factor and a tumor suppressor." (PMID 33508027, 2021). "MeDIP-qPCR and qPCR were performed to measure demethylation status and mRNA re-expression level of 7 tumor-suppressor genes (CCNA1, CHFR, FHIT, PAX1, PTEN, SFRP4, TSLC1) in Hela and Siha cells after silencing DNMT1." (PMID 21999220, 2011). "Although it is not direct evidence, a remarkably high protein level of the ΔFHA mutant, compared with that of the wild-type and other mutant forms of CHFR, suggests that the FHA domain has an important role in suppressing tumor formation." (PMID 18335050, 2008).
tumor (continued). "We find that both the anti-proliferative effects and checkpoint function of CHFR require the FHA domain, whereas the E3 ligase activity of this tumor suppressor relies on the RF and Cys domains." (PMID 18335050, 2008). "Additionally, CHFR (checkpoint protein with FHA and RING finger domains), a tumor suppressor, not only recognizes PARylation signaling at DNA damage sites but also demonstrates that the silencing of CHFR sensitizes GC to PARPi therapy." (PMID 37958290, 2023). "We show from our analysis that the loss of the RF domain and its associated E3 ligase activity did not disrupt the anti-proliferative effects of CHFR, suggesting that the E3 ligase activity of this protein is not essential for its tumor suppressor function." (PMID 18335050, 2008). "However, molecular pathways involved in the tumor suppressive function of CHFR are not yet clear since the two established roles of this protein are likely to inhibit cell growth." (PMID 18335050, 2008).
cancer (27 papers, 2004 to 2025). A tumor composed of atypical neoplastic, often pleomorphic cells that invade other tissues. "Loss of CHFR expression and promoter region hypermethylation were found frequently in different cancers." (PMID 25821560, 2015). "In recent years, it has become clear that CHFR promoter CpG island methylation is associated with a poor prognosis in multiple cancer types." (PMID 24375389, 2014). "A prominent example is the tumor suppressor protein, CHFR, which has been implicated in multiple human cancers, including EOC." (PMID 23351307, 2012). "The CHFR gene is often inactivated by methylation in cancer cells, and its methylation is associated with poor prognosis and increased sensitivity to paclitaxel in multiple cancer types, including ovarian and gastric cancers." (PMID 39902129, 2024). "Differential epigenetic regulation of CHFR has been identified in cancer as a result of promoter hypermethylation, or deacetylation of histones in the promoter region; however it is unclear whether changes in expression are a cause or consequence of cancer." (PMID 33436068, 2021). "For instance, the hypermethylation of CHFR, a gene involved in cell cycle checkpoint regulation, allows cancer cells to bypass normal checkpoints in response to DNA damage, leading to further genetic aberrations." (PMID 40959208, 2025). "CHFR (Checkpoint with Forkhead-associated and RING finger domains) plays a critical role in regulating mitotic entry and implicated in wide range of cancer." (PMID 40375984, 2025). "Although increasing studies focus on CHFR and its roles in multiple cancer types including GC were reported." (PMID 37024798, 2023). "The methylation level of CHFR has also been proved as a biomarker for predict the prognosis in several cancers." (PMID 37024798, 2023). "Several studies have suggested that CHFR expression is downregulated and inhibited by promoter hypermethylation in different types of cancer." (PMID 34539751, 2021). "It is also widely known that, in contrast with other cell cycle checkpoints, CHFR is mostly found methylated in cancer." (PMID 34869418, 2021). "The CCK8 assay indicated that cell proliferation was significantly lower for the cancer cells with CHFR knockdown than those with control siRNA transfection." (PMID 34539751, 2021). "We therefore evaluated the expression of CHFR in 33 different types of cancer from TCGA database and its relationship with prognosis." (PMID 34539751, 2021). "We found that CHFR was upregulated in many cancers, and high expression of CHFR in PRAD and LIHC also predicted poor prognosis." (PMID 34539751, 2021). "Epigenetic silencing of DNA repair genes such as MLH1, MGMT, BRCA1, FANCF, CHFR and SLFN11 can lead to gene mutations and genomic instability in cancer cells." (PMID 32974031, 2020). "Some studies have reported that CHFR expression is modulated by DNA methylation of its promoter, however, most of those studies are limited to detecting the CHFR DNA methylation levels in cancer tissues." (PMID 29367628, 2018). "Previous studies showed that CHFR level was elevated when cancer cells were stimulated with microtubule inhibitors, including paclitaxel, resulting in arrest of mitosis and escape from apoptosis induced by drugs." (PMID 29367628, 2018). "We further found that Aurora A, which is negatively regulated by CHFR and involved in regulating the sensitivity of cancer cells to paclitaxel, was synchronously increased following UBC13 knock-down and decreased with UBC13 up-regulation in both cells." (PMID 29367628, 2018). "CHFR promoter hypermethylation was observed in various human cancers including 20% in Non-Small Cell Lung Cancer (NSCLC), 30% in esophageal cancers, and 40% in CRC." (PMID 29179506, 2017). "In contrast to wild-type cancer cells, CHFR methylation led to an increased mitotic index in these cell lines treated with inhibitor of microtubule assembly." (PMID 29179506, 2017).
cancer (continued). "CHFR is a mitotic checkpoint and tumor suppressor gene, which is silenced in a variety of human cancers, mostly by promoter CpG island methylation." (PMID 29179506, 2017). "CHFR methylation has been found frequently in different cancers and is regarded as a marker of taxane sensitivity." (PMID 25821560, 2015). "In this study, we found that CHFR is infrequently methylated early in the esophageal carcinogenesis, but becomes more frequently methylated during the advanced cancer stage." (PMID 25821560, 2015). "Stronger support for the potential role for CHFR promoter CpG island methylation in predicting response to microtubule inhibitors has been described in other cancer types." (PMID 24375389, 2014). "Absence of CHFR in these cell lines resulted in a high mitotic index when exposed to microtubule stress compared to wild-type cancer cells, which was restored by reintroduction of functional CHFR." (PMID 24375389, 2014). "CHFR is more frequently inactivated in cancer than all other mitotic checkpoint control genes together." (PMID 24375389, 2014). "Since inactivation of CHFR promotes chromosomal defects and via activation of HDAC1 tissue invasion, CHFR malfunction is thought to play an important role in cancer progression and metastasis." (PMID 24375389, 2014). "Normal primary cells and cancer cell lines that express CHFR exhibit delayed entry into metaphase after treatment with microtubule inhibitors." (PMID 15138487, 2004). "Our findings suggest a complex role for CHFR in different cancers." (PMID 34539751, 2021). "The expression of CHFR in other cancers has also been investigated." (PMID 34539751, 2021). "Some previous experiments showed that targeting CHFR in cancer therapy is effective." (PMID 32943033, 2020). "Notably, in cancer cells with methylated CHFR, treatment with demethylation agent 5-aza-2-deoxycytidine led to re-expression of CHFR, and partially restored the prophase checkpoint." (PMID 29312643, 2017). "Methylation of CHFR has been shown to sensitize different cancers to taxane treatment." (PMID 25821560, 2015). "Methylation of CHFR has been regarded as a chemo-sensitive marker in various cancers." (PMID 25821560, 2015). "CHFR methylation has been reported to sensitize cancer cells to taxanes." (PMID 25821560, 2015). "In the last decade, a substantial number of studies have been performed to investigate CHFR inactivation, usually due to promoter CpG island methylation, as biomarker to predict prognosis and response to microtubule inhibitors in a diversity of cancers." (PMID 24375389, 2014). "Here we summarize literature on the relevance of altered CHFR expression in cancer." (PMID 24375389, 2014). "Furthermore, these results can be a rationale for studying the effect of taxane treatment in cancers with CHFR inactivation." (PMID 24375389, 2014). "In the last decade, disrupted CHFR expression has been described in multiple cancer tissues." (PMID 24375389, 2014). "Therefore, CHFR inactivation is expected to participate in the acquisition of chromosomal defects and a chromosomal instability phenotype in cancer." (PMID 24375389, 2014). "In most cancers, however, CHFR expression is reduced due to promoter CpG island methylation." (PMID 24375389, 2014). "In our previous study, we found that SGC-7901 and AGS cells expressed relatively lower levels of CHFR among several cancer cell lines, and the metastatic subtype SGC-7901 cells expressed higher level of CHFR compared with primary subtype AGS cells." (PMID 37024798, 2023). "CHFR, RASSF1A, P14, P15 and P16 genes are directly involved in cell cycle regulation and silenced by frequent methylation in different cancers." (PMID 32974031, 2020). "DDR and related genes were found frequently methylated in human cancers, including BRCA1/2, MGMT, WRN, MLH1, CHFR, P16 and APC." (PMID 32974031, 2020). "Moreover, CHFR could be a novel target for development of personalized cancer treatment." (PMID 29179506, 2017).
cancer (continued). "Correlations of RMVs between plasma samples and cancer tissues were found for CHFR (|r| = 0.458, p < 0.001), but not for SOX11 (|r| = 0.010, p = 0.94) and CDO1 (|r| = 0.011, p = 0.93)." (PMID 40666491, 2025). "The follow-up research showed that TRPV4 might affect the generation of cancer by influencing gene expression or function of SH3RF3, CHFR, ZTB1, and TRAFD1." (PMID 35813831, 2022). "In contrast, cancer cell lines that lack CHFR enter metaphase without delay, with ectopic expression of CHFR necessary and sufficient to restore cell-cycle delay." (PMID 15138487, 2004). "CHFR promoter methylation of ctDNA was found to be a negative prognostic factor for RFS in resectable Stage IV CRC in this study (#2) while that of cancer tissue gave a favorable PFS in advanced or metastatic CRC who underwent systemic chemotherapy with irinotecan-based regimen in Research #1." (PMID 40666491, 2025). "Although, an earlier study reported that CHFR could promote SIRT1 degradation under oxidant stress, whether CHFR took part in regulating in maintaining the redox homeostasis in cancer was not examined." (PMID 37024798, 2023). "Thus, CLIP-170, CHFR, and RNF8 all have pathological functions in cancer, and the potential interaction between CLIP-170 ubiquitination and CHFR or RING8 E3 ligases might have clinical implications, such as the therapeutic treatment of cancers." (PMID 36138017, 2022).
CHFR also shares sentences with these, for which no sentence is quoted: adenocarcinoma (3 papers); neuroblastoma (3); pancreatic cancer (3); prostate carcinoma (2); acute myeloid leukemia (1); bladder urothelial carcinoma (1); breast invasive carcinoma (1); cervical squamous cell carcinoma (1); cholangiocarcinoma (1); Clear Cell Renal Cell Carcinoma (1); diabetes (1); endocervical adenocarcinoma (1); endotoxemia (1); glioblastoma multiforme (1); glioma (1); kidney tumor (1); liver cancer (1); lung adenocarcinoma (1); lung carcinoma (1); Lynch syndrome (1); oligodendroglial tumor (1); paraganglioma (1); pheochromocytoma (1); pneumonia (1); prostate adenocarcinoma (1); stomach tumours (1); triple-negative breast carcinoma (1); uterine corpus endometrial carcinoma (1).